KCNK4 (potassium two pore domain channel subfamily K member 4)
Description:
K(+) channel that conducts voltage-dependent outward rectifying currents upon membrane depolarization. Voltage sensing is coupled to K(+) electrochemical gradient in an 'ion flux gating' mode where outward but not inward ion flow opens the gate. Converts to voltage-independent 'leak' conductance mode upon stimulation by various stimuli including mechanical membrane stretch, basic pH, heat and lipids. Homo- and heterodimerizes to form functional channels with distinct regulatory and gating properties. At trigeminal A-beta afferent nerves, the heterodimer of KCNK2/TREK-1 and KCNK4/TRAAK is mostly coexpressed at nodes of Ranvier where it conducts voltage-independent mechanosensitive and thermosensitive currents, allowing rapid action potential repolarization, high speed and high frequence saltatory conduction on myelinated nerves to ensure prompt sensory responses (By similarity). Permeable to other monovalent cations such as Rb(+) and Cs(+).
Synonyms: TRAAK; K2P4.1; FHEIG; TRAAK1
Tractability: Small molecule: a structure with a bound ligand is known; it belongs to a druggable protein family. Antibody: UniProt places it where antibodies can reach, with high confidence; its Gene Ontology location is reachable by antibodies, with high confidence; UniProt predicts a signal peptide or a membrane-spanning region.
Target class: Two-pore domain potassium channel; Voltage-gated ion channel; Ion channel; Potassium channels
Gene: Protein-coding gene on chromosome 11 (64,291,302 to 64,300,031, forward strand). Ensembl gene ENSG00000182450.
Subcellular location: Cell membrane; Cell projection, axon
Pathways (Reactome):
Muscle contraction: Phase 4 - resting membrane potential
Neuronal System: TWIK related potassium channel (TREK)
Gene Ontology:
Molecular function: mechanosensitive potassium channel activity; outward rectifier potassium channel activity; potassium channel activity; potassium ion leak channel activity; temperature-gated cation channel activity
Biological process: cellular response to acidic pH; cellular response to arachidonate; cellular response to fatty acid; cellular response to mechanical stimulus; potassium ion transmembrane transport; response to ultrasound; cellular response to alkaline pH; cellular response to temperature stimulus; detection of mechanical stimulus involved in sensory perception of touch; neuronal action potential; potassium ion transport; sensory perception of pain; sensory perception of temperature stimulus; memory; response to mechanical stimulus
Cellular component: plasma membrane; potassium channel complex; node of Ranvier; axon; membrane
Genetic constraint (gnomAD): Loss-of-function variants: 24 observed, 29.57 expected, observed/expected ratio (o/e) 0.81, 90% interval 0.59 to 1.14. The upper end of that interval is the gene's LOEUF score, 1.14, which puts it in group 5 of 6, group 1 being the genes least tolerant of losing a copy. Missense variants: 483 observed, 507.69 expected, observed/expected ratio (o/e) 0.95, 90% interval 0.88 to 1.03. Synonymous variants: 263 observed, 241.92 expected, observed/expected ratio (o/e) 1.09, 90% interval 0.98 to 1.2.
Gene-disease validity (ClinGen):
ClinGen rates the evidence that KCNK4 causes each of these diseases.
facial dysmorphism, hypertrichosis, epilepsy, intellectual/developmental delay, and gingival overgrowth syndrome (autosomal dominant): Moderate.
Homologues: Orthologues: chimpanzee KCNK4 (100% identical), macaque KCNK4 (99% identical), guinea pig KCNK4 (91% identical), pig KCNK4 (91% identical), dog KCNK4 (89% identical), mouse Kcnk4 (83% identical), rat Kcnk4 (83% identical), tropical clawed frog kcnk4 (54% identical), zebrafish kcnk4a (48% identical), Drosophila melanogaster Ork1 (25% identical), Caenorhabditis elegans twk-21 (23% identical), Caenorhabditis elegans twk-22 (21% identical), and 10 more. Paralogues in human: KCNK10 (41% identical), KCNK2 (38% identical), KCNK17 (25% identical), KCNK16 (24% identical), KCNK5 (24% identical), KCNK6 (22% identical), KCNK3 (22% identical), KCNK9 (22% identical), KCNK1 (21% identical), KCNK13 (21% identical), KCNK15 (21% identical), KCNK7 (20% identical), and 2 more.
Diseases named in the same sentence as KCNK4 in open-access papers:
KCNK4 is named in the same sentence as 35 diseases in open-access papers, as found by Europe PMC text mining. Sharing a sentence is not in itself a finding about the gene and the disease. The quoted sentences say what the papers report.
epilepsy (7 papers, 2019 to 2025). A brain disorder characterized by episodes of abnormally increased neuronal discharge resulting in transient episodes of sensory or motor neurological dysfunction, or psychic dysfunction. "Mutations in KCNK4 have been implicated in a neurodevelopmental syndrome, namely facial dysmorphism, hypertrichosis, epilepsy, intellectual/developmental delay, and gingival overgrowth syndrome (FHEIG, MIM# 618381)." (PMID 40230348, 2025). "The KCNK4 gene is potentially associated with a spectrum of phenotypes, ranging from mild isolated epilepsy, moderate EFS+ with partial FHEIG features, to severe FHEIG syndrome, which needs further studies in large cohorts." (PMID 40230348, 2025). "The KCNK4 gene was previously reported to be associated with facial dysmorphism, hypertrichosis, epilepsy, intellectual/developmental delay, and gingival overgrowth syndrome (FHEIG, OMIM# 618381)." (PMID 36683851, 2022). "The phenotypic spectrum of KCNK4-related diseases ranges from mild epilepsy to severe FHEIG syndrome, with moderate EFS+ with partial FHEIG features in between." (PMID 40230348, 2025). "By reviewing these cases, we have identified an emerging phenotypic spectrum of KCNK4 ranging from mild epilepsy, moderate EFS+ with partial FHEIG features, to severe FHEIG syndrome." (PMID 40230348, 2025). "This biased expression pattern in the brain is potentially one of the explanations for neurodevelopmental abnormalities and epilepsy as the phenotypic core of the KCNK4 gene." (PMID 40230348, 2025). "The phenotypic spectrum of KCNK4 potentially ranged from mild epilepsy such as Rolandic epilepsy to severe syndromic neurodevelopment disorder." (PMID 36683851, 2022). "This study suggested that the KCNK4 gene was potentially associated with epilepsy without other neurological phenotypes." (PMID 36683851, 2022). "Analysis of other eight cases with KCNK4 variants outlined the phenotypic spectrums of KCNK4, ranging from mild benign epilepsy, EFS+ with neurodevelopmental abnormalities, to syndromic neurodevelopmental disorders and revealed neurodevelopmental abnormalities and epilepsy as its core phenotypes." (PMID 40230348, 2025). "Previously, the KCNK4 gene has been reported to be associated with the FHEIG syndrome, which is featured by neurological phenotypes of intellectual disability and epilepsy, and the non-neurological phenotypes of facial dysmorphism, hypertrichosis, and gingival overgrowth." (PMID 40230348, 2025).
developmental delay (5 papers, 2019 to 2024). "There is notable overlap in the phenotypic findings of these syndromes associated with dominant KCNN3, KCNH1, and KCNK4 variants, sharing developmental delay and/or ID, coarse facial features, gingival enlargement, distal digital hypoplasia, and hypertrichosis." (PMID 33594261, 2021).
hypertrichosis (5 papers, 2019 to 2025). Excessive hair growth anywhere on the body. "Based on the data, the overarching phenotype associated with dominant KCNH1, KCNN3, and KCNK4 variants comprised DD and/or ID, hypotonia, coarsening facial features, gingival enlargement, and hypertrichosis." (PMID 33594261, 2021). "Similarly, all individuals with dominant KCNK4 variant (100%) had hypertrichosis, while only 3/16 (19%) and 3/6 (50%) with dominant KCNH1 and KCNN3 variant, respectively, showed hypertrichosis." (PMID 33594261, 2021). "A novel de novo KCNK4 variant (c.415G>A/p.Gly139Arg) was identified in a patient with EFS+, neurodevelopmental abnormalities, and hypertrichosis." (PMID 40230348, 2025). "Both features were consistently present in individuals with KCNK4 variant affecting function and variably present in patients with dominant KCNN3 (30% for hypertrichosis and 67% for gingival enlargement) or KCNH1 variant (19% for hypertrichosis and 79% for gingival enlargement)." (PMID 33594261, 2021).
Rolandic epilepsy (2 papers, 2022 to 2024). "Two novel likely pathogenic KCNK4 variants were identified in two unrelated cases, including one with Rolandic epilepsy and one with the FHEIG syndrome." (PMID 36683851, 2022). "In this study, we reported the first variant that is associated with Rolandic epilepsy, expanding the phenotypic spectrum of KCNK4." (PMID 36683851, 2022). "Such pleiotropy of KCNK4 is unexpected and low persuasive, and the pure epileptical phenotypes of KCNK4 are receivable (such as the Rolandic epilepsy in Case 1)." (PMID 36683851, 2022). "Two heterozygous missense variants (c.416G > A/ p.Gly139Glu and c.698C > T/p.Pro233Leu) in the KCNK4 gene were identified in two unrelated patients, including one with FHEIG syndrome and one with Rolandic epilepsy." (PMID 36683851, 2022).
Hypotonia (1 paper, 2021). Hypotonia is an abnormally low muscle tone (the amount of tension or resistance to movement in a muscle). "Hypotonia was present in 26/27 (96%) individuals with dominant KCNH1 variant, in 4/6 (67%) with dominant KCNN3 variant, and in 2/3 (66%) with dominant KCNK4 variant." (PMID 33594261, 2021).
Nail dysplasia (1 paper, 2021). The presence of developmental dysplasia of the nail. "In patients with dominant KCNK4 variant, nail dysplasia was absent, and data on specific finger and toe abnormalities were not reported." (PMID 33594261, 2021).
Nystagmus (1 paper, 2021). Rhythmic, involuntary oscillations of one or both eyes related to abnormality in fixation, conjugate gaze, or vestibular mechanisms. "The two individuals with the same KCNK4 variant affecting function [p.(Ala172Glu)] showed severe ID, and they were reported to have nystagmus with bilateral optic hypoplasia." (PMID 33594261, 2021).
thyroid cancer (1 paper, 2020). "This study implied that KCNK2, KCNK4, KCNK5 and KCNK15 are potential targets of precision therapy for patients with thyroid cancer and these genes are new biomarkers for the therapeutic target for thyroid cancer." (PMID 32742463, 2020). "In summary, by analyzing the differential expression of KCNKs genes, clinical staging analysis, prognosis analysis and functional enrichment analysis, we found that only four genes, KCNK2, KCNK4, KCNK5, and KCNK15, may play a role in the carcinogenesis of thyroid cancer." (PMID 32742463, 2020).
Zimmermann-Laband syndrome (1 paper, 2024). A rare disorder characterized by gingival fibromatosis, coarse facial appearance, and absence or hypoplasia of nails or terminal phalanges of hands and feet. "Clinical features of subjects with biallelic TBC1D2B pathogenic variants show phenotypic overlap with syndromic neurodevelopmental K+ channelopathies or Zimmermann-Laband syndrome associated with dominant KCNN3, KCNH1, and KCNK4 variants." (PMID 38374468, 2024).
cancer (3 papers, 2009 to 2021). A tumor composed of atypical neoplastic, often pleomorphic cells that invade other tissues. "Overexpression of members of the K2P family was associated with different cancer types with some exceptions, such as KCNK4 which was down-regulated." (PMID 31429720, 2019). "In addition, several of these genes have not previously been reported as methylated in any type of cancer (KCNK4, SEPT5, PENK, BMP4, TAL1, PGF, SMARCB1 (INI1), FRZB (SFRP3), IRAK3 and MCM2)." (PMID 19493342, 2009).
tumor (2 papers, 2009 to 2020). "Compared with tumor-adjacent tissues, KCNK5 and KCNK15 proteins were higher in PTC tissues and KCNK2 and KCNK4 proteins were lower in PTC, especially in PTC cytoplasm." (PMID 32742463, 2020).
KCNK4 also shares sentences with these, for which no sentence is quoted: neurodevelopmental disorder (4 papers); gingival overgrowth (3); Intellectual disability (3); amyotrophic lateral sclerosis (2); brain ischemia (1); Buruli ulcer (1); Cerebral ischemia (1); channelopathies (1); Cognitive impairment (1); colitis (1); Dravet syndrome (1); hypertensive diseases (1); infection (1); ischemia (1); melanoma (1); meningioma (1); migraine (1); Myocardial fibrosis (1); neuropathies (1); papillary thyroid carcinoma (1); spinal cord injuries (1); Stroke (1); Temple-Baraitser syndrome (1); Timothy syndrome (1).